NDOR1 (NADPH dependent diflavin oxidoreductase 1)
Description:
NADPH-dependent reductase which is a central component of the cytosolic iron-sulfur (Fe-S) protein assembly (CIA) machinery. Transfers electrons from NADPH via its FAD and FMN prosthetic groups to the [2Fe-2S] cluster of CIAPIN1, another key component of the CIA machinery. In turn, this reduced cluster provides electrons for assembly of cytosolic iron-sulfur cluster proteins. It can also reduce the [2Fe-2S] cluster of CISD1 and activate this protein implicated in Fe/S cluster repair. In vitro can fully activate methionine synthase/MTR in the presence of soluble cytochrome b5/CYB5A.
Synonyms: NR1; bA350O14.9; CIAE1
Tractability: Small molecule: a structure with a bound ligand is known. PROTAC: ubiquitination databases record sites on it; its protein half-life has been measured.
Gene: Protein-coding gene on chromosome 9 (137,205,667 to 137,219,361, forward strand). Ensembl gene ENSG00000188566.
Subcellular location: Cytoplasm, perinuclear region
Subcellular location (Human Protein Atlas): Cytosol; Intermediate filaments; Nucleoplasm
Pathways (Reactome):
Metabolism: Cytosolic iron-sulfur cluster assembly
Gene Ontology:
Molecular function: electron transfer activity; FAD binding; FMN binding; NADP binding; NADPH binding; NADPH-hemoprotein reductase activity; NADPH-iron-sulfur [2Fe-2S] protein oxidoreductase activity; oxidoreductase activity, acting on NAD(P)H, heme protein as acceptor; protein binding; flavin adenine dinucleotide binding; oxidoreductase activity; oxidoreductase activity, acting on NAD(P)H
Biological process: electron transport chain; cellular response to oxidative stress; iron-sulfur cluster assembly
Cellular component: cytoplasm; cytosol; cytosolic [4Fe-4S] assembly targeting complex; perinuclear region of cytoplasm
Genetic constraint (gnomAD): Loss-of-function variants: 62 observed, 66.24 expected, observed/expected ratio (o/e) 0.94, 90% interval 0.76 to 1.16. The upper end of that interval is the gene's LOEUF score, 1.16, which puts it in group 5 of 6, group 1 being the genes least tolerant of losing a copy. Missense variants: 878 observed, 780.98 expected, observed/expected ratio (o/e) 1.12, 90% interval 1.06 to 1.19. Synonymous variants: 378 observed, 335.2 expected, observed/expected ratio (o/e) 1.13, 90% interval 1.04 to 1.23.
Homologues: Orthologues: chimpanzee NDOR1 (99% identical), macaque NDOR1 (96% identical), guinea pig NDOR1 (83% identical), pig NDOR1 (83% identical), mouse Ndor1 (82% identical), rat Ndor1 (81% identical), dog NDOR1 (71% identical), tropical clawed frog ndor1 (60% identical), zebrafish ndor1 (59% identical), Caenorhabditis elegans fre-1 (39% identical), Drosophila melanogaster CG13667 (38% identical). Paralogues in human: POR (31% identical), MTRR (30% identical), NOS1 (27% identical), NOS3 (27% identical), NOS2 (26% identical).
Diseases named in the same sentence as NDOR1 in open-access papers:
NDOR1 is named in the same sentence as 4 diseases in open-access papers, as found by Europe PMC text mining. Sharing a sentence is not in itself a finding about the gene and the disease. The quoted sentences say what the papers report.
diabetes (1 paper, 2024). "We used machine learning to identify six key genes closely associated with vascular aging in diabetes: TFB1M, FOXRED2, LY75, DALRD3, PI4K2B, and NDOR1." (PMID 38809515, 2024). "The expression of TFB1M, FOXRED2, DALRD3, PI4K2B, and NDOR1 was negatively correlated with vascular aging in diabetes, while LY75 expression was positively correlated." (PMID 38809515, 2024). "Using bioinformatics and machine learning techniques, we identified six key genes that are closely associated with vascular aging in diabetes: TFB1M, FOXRED2, LY75, DALRD3, PI4K2B, and NDOR1." (PMID 38809515, 2024).
lymph node metastasis (1 paper, 2022). "ATP7A (P = 0.007), LIPT1 (P = 0.009), DLAT (P = 0.006) and NDOR1 (P = 0.039) expression were remarkably interrelated to lymph node metastasis (N classification)." (PMID 36313717, 2022).
cancer (2 papers, 2008 to 2022). A tumor composed of atypical neoplastic, often pleomorphic cells that invade other tissues. "DDB0187719 (redC) on chromosome 5 encodes a polypeptide of 633 amino acids, which is 56% similar to human NADPH-dependent diflavin oxidoreductase 1 (NDOR1), a cytoplasmic enzyme highly expressed in cancer cell lines with as yet unknown functions." (PMID 18218133, 2008).
NDOR1 also shares sentences with these, for which no sentence is quoted: tumor (1 paper).